MSX2 (msh homeobox 2)
Diseases named in the same sentence as MSX2 in open-access papers (continued):
Sharing a sentence is not in itself a finding about the gene and the disease.
cancer (14 papers, 2009 to 2023). A tumor composed of atypical neoplastic, often pleomorphic cells that invade other tissues. "Higher expression of MSX2 was found to be associated with metastasis in different types of human cancers." (PMID 27935967, 2016). "The MSX2 interacts with SOX2 to control cancer stem cell-like characterization in oral squamous cell carcinoma (SCC)." (PMID 38110859, 2023). "Recently, MSX2 was found to play important roles in the invasion of cancer cells into adjacent tissues via the epithelial-mesenchymal transition (EMT)." (PMID 27088357, 2016). "Previous studies demonstrated that MSX2 promotes EMT through activation of the Wnt/β-catenin signaling pathway in cancer cells." (PMID 27088357, 2016). "In gastric cancer, MSX2 was identified as a cancer-specific hedgehog target and the down-regulation of this gene resulted in the inhibition of cancer cell growth in vitro." (PMID 23162473, 2012). "The dominant MSX2 expression in cancer cells was also reported in other carcinomas such as bile duct, stomach, and breast." (PMID 23162473, 2012). "The correlation between the up-regulation of MSX2 and clinicopathological factors was investigated in a number of carcinomas." (PMID 23162473, 2012). "Recent studies revealed the roles of MSX2 in the development of carcinoma of various origins including pancreas." (PMID 23162473, 2012). "MSX2 interacts with SOX2 in oral SCC to control cancer stem cell-like traits." (PMID 38110859, 2023). "Furthermore, it has been reported that some of these genes (e.g. Foxa2 and Msx2) are able to change gene expression patterns in human cancer." (PMID 27711132, 2016). "In addition, while earlier reports detected elevated MSX2 expression in a variety of carcinoma cell lines, more recent studies demonstrated that MSX2 promotes EMT through activation of Wnt signaling in cancer cells." (PMID 27088357, 2016). "In addition, the enhanced expression of MSX2 has been shown in a variety of carcinoma cell lines of epithelial origin compared to their corresponding normal tissues." (PMID 23162473, 2012). "The distal 5q35.2q35.3 contains the homeobox MSX2, MGAT1 and BTNL3 respectively involved in embryonic development and cancer." (PMID 22253721, 2012). "Furthermore, we identified two cancer-specific Hh targets, ELK1 and MSX2, which have an essential role in GC cell growth." (PMID 19107131, 2009). "Furthermore, we identified two cancer-specific Hh targets, ELK1 and MSX2, which have an essential role in tumour cell growth." (PMID 19107131, 2009). "PIK3CA-mutant cancers displayed higher expression of 12 of the 17 Wnt genes compared to PIK3CA wild-type tumors, including five Wnt target genes (LEF1, MYCN, FZD7, SFRP2, and TNFRSF11B) and seven Wnt signaling components (TCF7L1, TCF7L2, CTNNB1, FZD4, SFRP1, WNT5A, and MSX2)." (PMID 34035258, 2021). "While trophoblastic cells and cancer cells exhibit several similar behavioral characteristics, including the mechanism by which they invade adjacent tissues via EMT, it is currently unclear whether MSX2 plays a role in regulating trophoblast cell invasion during embryo implantation." (PMID 27088357, 2016). "Despite the lack of modulation of PRAME by MSX2, it will be of enormous interest to further explore how PRAME controls human mesenchymal development and whether PRAME promotes carcinogenesis by giving the cells mesenchymal characteristics during cancer progression." (PMID 30033084, 2018).
cardiovascular disease (1 paper, 2025). "Vascular calcification is a hallmark of advanced cardiovascular disease, caused by VSMC phenotypic switching from a contractile to an osteogenic state marked by RUNX2, MSX2, and ALP expression." (PMID 41189994, 2025).
vasculopathies (1 paper, 2014). "For the induction of an osteochondrogenic phenotype, the contribution of TGFβ signalling, BMPs-SMADs-RUNX2 signalling, Wnt-MSX2 signalling, apoptosis, oxidative stress and ER stress are well appreciated in calcified vasculopathies." (PMID 24775865, 2014). "Its upregulation has been observed in calcified vasculopathies, together with MSX2 and OSX, confirming its role in soft tissue mineralization, where it induces VSMC to acquire an osteogenic phenotype." (PMID 24775865, 2014).
MSX2 also shares sentences with these, for which no sentence is quoted: oral squamous cell carcinoma (2 papers); adenocarcinoma (1); anemia (1); ankylosis (1); autism spectrum disorder (1); brachydactyly (1); brain tumor (1); breast ductal carcinomas (1); chronic renal failure (1); Coronal craniosynostosis (1); Cranial meningocele (1); craniofrontonasal syndrome (1); endometrioid endometrial carcinomas (1); enthesitis (1); epilepsy (1); glioblastoma (1); hepatoblastoma (1); Hunter–McAlpine syndrome (1); Hypercalcemia (1); hypophosphatasia (1); insulin-resistant (1); Intellectual disability (1); intestinal tumor (1); lung adenocarcinoma (1); mandibuloacral dysplasia (1); megalencephalic leukoencephalopathy with subcortical cysts (1); metabolic disease (1); Microdontia (1); nephrocalcinosis (1); Obesity (1).
A further 13 diseases each share a sentence with MSX2 in 1 paper.